CFTR (CF transmembrane conductance regulator)
Diseases named in the same sentence as CFTR in open-access papers (continued):
Sharing a sentence is not in itself a finding about the gene and the disease.
cystic fibrosis (continued). "Chronic lung infections in CF patients are associated with defective apical ion transport due to mutations in the gene encoding the cystic fibrosis transmembrane conductance regulator (CFTR)." (PMID 33692800, 2021). "The ultimate goal for DNA-based therapies in cystic fibrosis is to target and correct enough stem cells with a single administration to populate the airways and restore CFTR function throughout the patient’s lifespan." (PMID 34685773, 2021). "The pharmacokinetic (PK) data available for ivacaftor-lumacaftor cystic fibrosis transmembrane conductance regulator (CFTR) modulator drug combination is limited." (PMID 34408649, 2021). "The cystic fibrosis gene, CFTR, was firstly identified in 1989, is located at the 7q13 position, and spans ~190 kilobases (kb) on chromosome 7q31.2 with 27 exons." (PMID 33572515, 2021). "The ΔF508 mutant form of the cystic fibrosis transmembrane conductance regulator (CFTR), the most common cause of cystic fibrosis, is retained, despite its local function being effectively degraded by ERAD." (PMID 34422051, 2021). "One of the most common cholangiopathies, cystic fibrosis, is caused by a mutation in the cystic fibrosis transmembrane conductance regulator (CFTR) that encodes a chloride ion channel expressed by the cholangiocyte and responsible for the regulation of bile secretion." (PMID 34764255, 2021). "In CF, mutations in the gene encoding the cystic fibrosis transmembrane conductance regulator (CFTR) protein impair transepithelial electrolyte and water transport, resulting in airway dehydration, and a thickening of the mucus associated with abnormal viscoelastic properties." (PMID 34253193, 2021). "Ivacaftor (VX-770) was the first cystic fibrosis transmembrane conductance regulator (CFTR) modulatory drug approved for the treatment of patients with cystic fibrosis." (PMID 34142049, 2021). "For example, a cystic fibrosis transmembrane conductance regulator (CFTR) knockout mouse model was used to study cystic fibrosis and the QS inhibiting effects of azithromycin against P. aeruginosa biofilms." (PMID 33927701, 2021). "New drugs called CFTR modulators aim at restoring the CFTR protein function, and they will benefit many patients with cystic fibrosis in the near future." (PMID 34685773, 2021). "The importance of understanding the intracellular pathways and intracellular localization of CFTR protein opens new targets for pharmacological intervention in cystic fibrosis patients." (PMID 34832033, 2021). "In fact, a so-called cystic fibrosis gender gap describes the higher mortality in females with CF, due to lower expression of CFTR." (PMID 34199520, 2021). "In patients with the genetic condition cystic fibrosis, mutations in the cystic fibrosis transmembrane conductance regulator (CFTR) gene results in multi-organ dysfunction; however mortality is primarily attributed to progressive lung disease and respiratory failure." (PMID 34680757, 2021). "There has been remarkable progress made in the use of patient tissue-derived primary organoids for the in vitro modeling of Cystic Fibrosis pathogenesis and testing of therapies targeting mutant Cystic Fibrosis Transmembrane Conductance Regulator (CFTR)." (PMID 34943927, 2021). "CandActCFTR is a pilot project to merge data from publicly available sources and establish a database of candidate cystic fibrosis therapeutics for the activation of CFTR-mediated ion conductance." (PMID 34955819, 2021). "The aim of this study was the identification of specific proteomic profiles, related to a restored cystic fibrosis transmembrane conductance regulator (CFTR) activity in cystic fibrosis leukocytes before and after ex vivo treatment with the potentiator VX770." (PMID 33920274, 2021).
cystic fibrosis (continued). "Cystic Fibrosis is an autosomal recessive condition caused by mutations in the CF transmembrane conductance regulator (CFTR) gene, which encodes a chloride/bicarbonate channel important for maintaining ion homeostasis across epithelial membranes, perhaps most essentially in the airways." (PMID 34828417, 2021). "Cystic fibrosis is the most commonly, still fatal, inherited genetic disease in Caucasian populations, caused by a mutation in the cystic fibrosis transmembrane conductance regulator (CFTR) gene coding for a transmembrane channel allowing the transport of chloride ions." (PMID 33919046, 2021). "Human lung diseases, viz., cystic fibrosis causing a mutation in the cystic fibrosis transmembrane regulator (CFTR), was modified precisely by CRISPR-edited corrective CFTR sequences." (PMID 33805113, 2021). "For many people with cystic fibrosis (pwCF), CFTR modulators will be the cornerstone of their treatment." (PMID 34073663, 2021). "CF is caused by mutations of the cystic fibrosis transmembrane conductance regulator (CFTR) gene, which encodes a membrane protein that serves as a chloride and bicarbonate channel in exocrine epithelia of various organs, and thereby regulates the viscosity of the mucus lining." (PMID 34299207, 2021). "Here, we apply this approach in human organoids to introduce cancer mutations and to repair mutations in the cystic fibrosis transmembrane conductance regulator (CFTR) channel that cause cystic fibrosis, a Mendelian disorder with high prevalence in European ancestry." (PMID 34373320, 2021). "The most frequent tested genes were spinal muscular atrophy (SMA), cystic fibrosis (CFTR), and phenylketonuria (PAH)." (PMID 33197157, 2021). "Highly effective CFTR modulators such as elexacaftor/tezacaftor/ivacaftor (ELE/TEZ/IVA will become available for an increasing number of people with cystic fibrosis (pwCF) in the near future." (PMID 34442455, 2021). "The endogenous CFTR expression, for example in the cystic fibrosis bronchial epithelium cell line CFBE41o- (F508del/F508del), allows to correlate genomic CFTR correction with functional rescue at the protein level." (PMID 33986686, 2021). "The gene encoding for this channel is altered in cystic fibrosis and, for this reason, it is called CFTR (cystic fibrosis transmembrane conductance regulator)." (PMID 34835466, 2021). "The purpose of this study was to compare the nutritional status between deltaF508 CFTR hetero- and homozygous paediatric patients with cystic fibrosis." (PMID 33919435, 2021). "Advancements in rescuing mutation-derived phenotypes of ABC transporters are largely driven by the research on CFTR, as cystic fibrosis is a frequent hereditary disease with adverse outcomes." (PMID 33801813, 2021). "Lentivirus-mediated gene expression in mouse lung epithelium has been investigated as a treatment for cystic fibrosis and provides long term expression of the cystic fibrosis transmembrane conductance regulator (CFTR)." (PMID 34214142, 2021). "These “correctors” and “potentiators” affect the cystic fibrosis transmembrane conductance regulator (CFTR), an ATP-gated anion channel, mutated in those with cystic fibrosis." (PMID 34290673, 2021). "Defective CFTR biogenesis and activity in cystic fibrosis airways leads to airway dehydration and impaired mucociliary clearance, resulting in chronic airway infection and inflammation." (PMID 34831482, 2021). "Remarkable progress in CFTR research has led to the therapeutic development of modulators that rescue the basic defect in cystic fibrosis." (PMID 34947992, 2021). "Mutations in the cystic fibrosis transmembrane conductance regulator (CFTR) protein lead to persistent lung bacterial infections, mainly due to Pseudomonas aeruginosa, causing loss of respiratory function and finally death of people affected by CF." (PMID 34971429, 2021).
cystic fibrosis (continued). "CBAVD is usually discovered in adult men either during the systematic assessment of cystic fibrosis or other CFTR-related conditions, or during the exploration of isolated infertility with obstructive azoospermia." (PMID 32025909, 2021). "Eluforsen was shown to improve CFTR function in cell and animal models of p.Phe508del-CFTR-mediated cystic fibrosis." (PMID 34685773, 2021). "Decreased CFTR expression (KE1) in airway epithelium has been observed in cystic fibrosis and after hypoxia and cigarette smoke exposure, resulting in reduced Cl− transport and, ultimately, reduced ASL depth." (PMID 35295103, 2021). "ABCC7 (cystic fibrosis transmembrane conductance regulator, CFTR) is an ATP-sensitive chloride channel mutated in patients with cystic fibrosis." (PMID 34955897, 2021). "CF is an autosomal recessive genetic disease frequent in the Caucasian population caused by mutations in the cystic fibrosis transmembrane conductance regulator (CFTR) gene." (PMID 34970510, 2021). "There is limited safety data available for non-cystic fibrosis patients; however, CFTR therapeutics have been shown to be well-tolerated in a small cohort of healthy volunteers and smokers with chronic obstructive pulmonary disease." (PMID 34367053, 2021). "Since the cloning of the CFTR gene in 1989 and the subsequent growing knowledge of the CFTR protein’s maturation, structure and function, the development of drugs correcting the basic defect in cystic fibrosis has been a major goal." (PMID 34685773, 2021). "In cellula experiments demonstrated that PGD97 is able to stabilize ∆F508 CFTR and improve CFTR functions, representing a potential novel treatment for cystic fibrosis." (PMID 34641953, 2021). "Cystic fibrosis is a genetic disease characterized by CF transmembrane regulator (CFTR) dysfunction." (PMID 33441643, 2021). "Cystic fibrosis transmembrane conductance regulator (CFTR) modulators have transformed the treatment of cystic fibrosis by targeting the basis of the disease." (PMID 34604301, 2021). "Our understanding of cystic fibrosis has grown exponentially since the discovery of the cystic fibrosis transmembrane conductance regulator (CFTR) gene in 1989." (PMID 33924524, 2021). "Mutations in the CFTR gene, which encodes for this protein, cause the disease cystic fibrosis." (PMID 34578785, 2021). "Cystic fibrosis is the most common worldwide, life-shortening multisystem hereditary disease, with an autosomal recessive inheritance pattern caused by mutations in the cystic fibrosis transmembrane conductance regulator (CFTR) gene." (PMID 33920345, 2021). "Lung and intestinal organoids derived from cystic fibrosis patients are currently being used to develop cystic fibrosis transmembrane conductance regulator (CFTR) modulating therapies." (PMID 34202980, 2021). "CF is caused by mutations occurring in the CFTR gene encoding for the Cystic Fibrosis Transmembrane Conductance Regulator protein, a chloride-permeable channel expressed in epithelial cells of various organs, including the lungs, pancreas, intestine, liver, and sweat glands." (PMID 34067708, 2021). "Cystic fibrosis (CF; MIM:219700) is a monogenic disorder that is caused by pathogenic variants in the cystic fibrosis transmembrane conductance regulator (CFTR) gene (MIM:602421)." (PMID 34054511, 2021). "The development of CFTR modulator therapies significantly changed the treatment scheme of people with cystic fibrosis." (PMID 33816324, 2021). "Since the discovery of the CFTR gene in 1989, we are now able to diagnose cystic fibrosis (MIM: 602421) rapidly, predict pancreatic functional status, and plan preventative care with modulator therapy." (PMID 34220947, 2021). "The cystic fibrosis transmembrane conductance regulator (CFTR) protein is a cAMP-activated anion channel that is critical for regulating fluid and ion transport across the epithelium." (PMID 34708042, 2021).
cystic fibrosis (continued). "CF is caused by mutations in the cystic fibrosis transmembrane regulator (CFTR) gene, which encodes for a cAMP-dependent anion channel that mediates chloride and bicarbonate transport at the apical membrane of epithelial cells of airways, pancreas, liver, intestine, and sweat glands." (PMID 34769402, 2021). "Cystic fibrosis (CF, OMIM #219,700) is a rare, autosomal recessive, monogenetic disease caused by mutations in the cystic fibrosis transmembrane conductance regulator (CFTR) gene." (PMID 34213646, 2021). "Mutations in the CFTR gene cause the hereditary life shortening disease cystic fibrosis." (PMID 33178018, 2020). "Despite recent advances, the pharmacological therapy of cystic fibrosis, an autosomal recessive genetic disorder caused by the mutation of the cystic fibrosis transmembrane conductance regulator (CFTR or ABCC7) gene, is still a largely unmet medical need." (PMID 32512832, 2020). "For example, in cystic fibrosis patients homozygous for the ΔF508 mutation (deletion of a phenylalanine at site 508) in the CFTR gene, the misfolded protein in endoplasmic reticulum (ER) is mostly degraded after failing to go through the quality control system." (PMID 32780246, 2020). "CF, which is caused by mutations of the cystic fibrosis transmembrane conductance regulator gene (human, CFTR; murine, Cftr), is the most common recessively-inherited disorder in North America and Europe, with more than 80,000 CF patients in the EU and the USA alone." (PMID 32327486, 2020). "CF is a genetic disease, which causes a defective ion transfer through the epithelial cellular membranes (cystic fibrosis transmembrane conductance regulator (CFTR) chloride channels)." (PMID 32933070, 2020). "We provide a roadmap through technologies and strategies tailored to correct different types of mutations in the cystic fibrosis transmembrane regulator (CFTR) gene, and their applications for the development of experimental models valuable for the advancement of CF therapies." (PMID 32486152, 2020). "Reduced CFTR (ABCC7) function is associated with cystic fibrosis (CF; OMIM 219700)." (PMID 32206879, 2020). "With the recent advances in cystic fibrosis transmembrane conductance regulator (CFTR) modulator therapies and the substantial increase in life expectancy of individuals with cystic fibrosis, novel challenges are emerging at the forefront of this disease." (PMID 32365523, 2020). "Over the last years CFTR (cystic fibrosis transmembrane conductance regulator) modulators have shown the ability to improve relevant clinical outcomes in patients with cystic fibrosis." (PMID 32824306, 2020). "Moreover, the rare genetic disease cystic fibrosis is caused by defects in the anion-selective channel protein cystic fibrosis transmembrane conductance regulator (CFTR) due to mutations in the CFTR-encoding gene." (PMID 32168979, 2020). "Cystic fibrosis is a monogenic disease, and the insertion of the functional CFTR gene into CF patient cells should theoretically restore the CFTR channel function." (PMID 32575461, 2020). "One example is the treatment of cystic fibrosis, where genotyping of the CFTR gene directly impacts the likelihood for successful treatment using CFTR modulators." (PMID 32226396, 2020). "The resulting dataset also contained two known recessive disease causing variants with evidence of heterozygote advantage in the sickle-cell anemia (HBB) and cystic fibrosis (CFTR)." (PMID 32231685, 2020). "In the CFTR knockout mice mouse model of cystic fibrosis, NorUDCA leads to increased biliary bicarbonate and fluid secretion." (PMID 32432119, 2020). "Cystic fibrosis is an autosomal recessive genetic disease caused by a mutation in the gene encoding the cystic fibrosis transmembrane conductance regulator channel (CFTR)." (PMID 33117337, 2020).
cystic fibrosis (continued). "CF is caused by a mutation in the gene responsible for the synthesis of the CFTR (cystic fibrosis transmembrane conductance regulator) chloride channel, altering the mucosal function in the respiratory epithelium, pancreatic ducts, intestines, and sweat glands." (PMID 32575461, 2020). "In this context, we performed a study using CFBE cells, initially from an individual with cystic fibrosis homozygous for the F508del CFTR." (PMID 32326361, 2020). "Given the importance of the proper regulation of plasma membrane levels of E-cadherin and MMP14 in cancer and of CFTR in cystic fibrosis, it is essential to identify the molecular pathways that control their trafficking." (PMID 32344433, 2020). "This case adds to the limited body of evidence that CFTR modulators lead to the improvement of pancreatic exocrine function in cystic fibrosis." (PMID 31940891, 2020). "We employ HIOs generated in this way to measure CFTR function using cystic fibrosis patient-derived iPSC lines before and after correction of the CFTR mutation, demonstrating their future potential for disease modeling and therapeutic screening applications." (PMID 31924806, 2020). "Mutations in the CFTR gene affect chloride channel function, resulting in the dysregulation of epithelial fluids and salt transport in many organs, including the lung, stomach, and intestinal digestive system, ultimately causing cystic fibrosis." (PMID 32104192, 2020). "The recent proof-of-concept experiments using stem-cell organoids from patients with cystic fibrosis confirmed that targeting CFTR with small molecules is both rational and effective." (PMID 34541464, 2020). "We find that 1543 genes, including CFTR, show differential expression in the colon of cystic fibrosis patients compared to healthy controls." (PMID 31992345, 2020). "A dysfunctional CFTR leads to the dehydration of the external environment of the cells and to the production of viscous mucus in the airways of cystic fibrosis patients." (PMID 32469934, 2020). "Lentiviral-mediated integration of a CFTR transgene cassette into airway basal cells is a strategy being considered for cystic fibrosis cell-based therapies." (PMID 33036232, 2020). "Overall, this study highlights the beneficial effects of a phosphorylated form of HspB5 on F508del-CFTR rescue and its therapeutic potential in cystic fibrosis." (PMID 32650630, 2020). "Progress in the survival and quality of life of Cystic Fibrosis patients, until the recent advent of CFTR potentiators and/or modulators depended on the intensity of the diagnostic therapeutic program and the compliance." (PMID 32234058, 2020). "Cystic fibrosis is a genetic disease resulting from mutations in the cystic fibrosis transmembrane conductance regulator (CFTR) and causes premature death by progressive respiratory failure, itself caused by lung destruction from a vicious circle of infection and inflammation." (PMID 32849617, 2020). "4PBA has also been tested with the mutant channel Δ508-CFTR-inducing cell surface expression, and some clinical trials using this chemical chaperone in cystic fibrosis patients have demonstrated an improvement in CFTR function in the nasal epithelia." (PMID 32392767, 2020). "Cystic fibrosis is a genetic disease in which people have decreased mucociliary clearance in the respiratory tract, due to mutations in the cystic fibrosis transmembrane conductance regulator (CFTR) gene, which encodes a chloride channel." (PMID 32983077, 2020). "This mutation cause cystic fibrosis and, when corrected using ACE-tRNATrp (engineered to insert W at PTC), results in the production of mature glycosylated CFTR protein (W1282W) localized to the plasma membrane." (PMID 32967234, 2020). "Molecular analysis of CFTR gene is a key step in the diagnosis of Cystic Fibrosis, carrier testing and prenatal diagnosis; it represent the most frequent genetic test carried out in Italy." (PMID 32234058, 2020).